CD4 (CD4 molecule)
Diseases named in the same sentence as CD4 in open-access papers (continued):
Sharing a sentence is not in itself a finding about the gene and the disease.
pulmonary edema (3 papers, 2012 to 2020). Accumulation of fluid in the lung tissues causing disturbance of the gas exchange that may lead to respiratory failure. "Notably, Wang and colleagues previously found that CD4 T-cells, CD8 T-cells, and NK cells are depleted in patients with pulmonary oedema, possibly resulting in impaired EV-A71 clearance." (PMID 32741368, 2020).
red cell aplasia (3 papers, 2014 to 2023). "In our series, the most common paraneoplastic syndrome was pure red cell aplasia which may be due to lacking of the capacity to propagate the maturation of immature naive CD4 T cells and export mature naive T cells into the periphery." (PMID 32607118, 2019).
reovirus infection (3 papers, 2021 to 2023). "Although the dependence on NK cells could be because of their early role in recruiting sDCs to initiate anti-tumor immunity, the demonstration that the CD4+ T cells were the most potent producers of IFNg in response to reovirus infection supports their direct role in control of tumor growth." (PMID 33665363, 2021). "As control, U87-MG and MNT-1 cells were engineered to stably express CD4 on their surface, and no significant changes were seen in CD4 surface expression upon reovirus infection." (PMID 37753084, 2023).
retinal detachment (3 papers, 2014 to 2021). An eye emergency condition which may lead to blindness if left untreated. "The median CD4 count of the 6 patients who had IRU just prior to retinal detachment was 154 cells/μL (range 20-333 cells/μL) compared to 68 cells/μL (range 15-571 cells/μL) in the patients who did not have IRU (p = 0.840)." (PMID 25429876, 2014). "All cases of retinal detachment had CD4-count less than 100 cell/mm3." (PMID 27355047, 2014).
retinoblastoma (3 papers, 2020 to 2025). A malignant tumor that originates in the nuclear layer of the retina. "Our analysis revealed that the TME in retinoblastoma predominantly consists of multiple immune cell types, including CD4+ T cells and antigen presenting cells." (PMID 40395327, 2025). "To elucidate the cellular landscape of human retinoblastoma, we first performed transcriptome-based cell type deconvolution analysis using xCell, revealing high abundance of various immune cell types in retinoblastoma, most prominently CD4+ T helper cells, as well as pericytes and fibroblasts." (PMID 40395327, 2025).
Schistosomiasis japonica (3 papers, 2015 to 2024). Schistosomiasis caused by Schistosoma japonicum. "In Schistosomiasis japonica and mansoni, parasite eggs were trapped in host liver and stimulated the CD4+T cell responses to regulate the formation of the granulomas." (PMID 25604731, 2015). "Next, we compared the frequencies of total peripheral memory Tfh cells (CXCR5+CD45RA-CD4+ T cells) and activated peripheral memory Tfh cells (PD-1+ICOS+Tfh cells) among CD4+ T or total peripheral memory Tfh cells in 50 patients with schistosomiasis japonica to 50 healthy controls." (PMID 26284362, 2015).
shigellosis (3 papers, 2012 to 2021). Shigellosis is a bacterial infection leading to dysentery and is caused by Shigella, which are small, ubiquitous Gram-negative bacteria belonging to the enterobacteria family. "There were limited data in our study on CD4 count and HIV load, so we were unable to explore whether these factors were associated with shigellosis severity." (PMID 34908501, 2021). "Infiltration of the surface epithelium and lamina propria by γδ+ CD4+ and CD8+ T-cells occurs in human shigellosis with CD3+CD4+FoxP3+ T regulatory (Treg) cells maintaining gut tolerance by suppressing local antigen specific immune responses to commensal bacteria." (PMID 22887873, 2012).
skin reaction (3 papers, 2022 to 2025). "The baseline frequency of CD69+CD4+ T cells was higher in subjects who presented with skin reactions during benznidazole therapy than that of the uninfected group, whereas the frequency of CD69+CD8+ T cells was not different among groups." (PMID 35938810, 2022).
skin sensitization (3 papers, 2021 to 2024). An immunological response to previous exposure to a substance which results in an inflammatory skin reaction. "This, in turn, leads to the activation of hapten-specific CD4+ and CD8+ T cells, typically assessed as a measure of skin sensitization." (PMID 39201318, 2024).
small bowel enteropathy (3 papers, 2020 to 2022). "Higher colonic inflammation and small bowel enteropathy due to transfer of CD4+ T cells in animal models." (PMID 36039239, 2022). "An inflammatory response occurs, as CD4+ cells mainly secrete Th1 cytokines (as INF-gamma) that result in small bowel enteropathy, which is characterized by mucosal remodeling, villus atrophy and increasing cytotoxicity of intraepithelial lymphocytes or natural killer (NK) T-cells." (PMID 32290294, 2020).
soft tissue sarcoma (3 papers, 2016 to 2025). A malignant neoplasm arising from muscle tissue, adipose tissue, blood vessels, fibrous tissue, or other supportive tissues excluding the bones. "Existing studies have shown that in the mouse soft tissue sarcoma model, antibody blockade of LAG-3 can significantly inhibit tumor growth and increase the secretion level of IFN-γ in CD8+ cytotoxic T cells and CD4+ helper T cells." (PMID 40761795, 2025). "The positivity of CD4, CD8, and CD34 markers was associated with a low degree of aggressiveness of soft-tissue sarcomas, without invasion of the tumor margins, thus illustrating a better survival rate in these patients." (PMID 40362599, 2025). "CD4, CD8, and CD34 marker positivity was linked to soft-tissue sarcomas that were less aggressive and did not invade the tumor margins, indicating a higher survival percentage for these individuals." (PMID 40362599, 2025).
Streptococcus pneumonia (3 papers, 2020 to 2024). "A previous study showed T cell function impairment, CD4+ T cell reduction, and pathogen-specific memory Th17 cell response impairment to Streptococcus pneumonia in diabetic patients." (PMID 39026159, 2024).
systemic vasculitis (3 papers, 2014 to 2024). "By contrast, both CD4+ and CD8+ T-cells were proliferating in the affected skin, with both containing cytotoxic granzyme B. In addition, our data have demonstrated that plasma sPD-L1 was positively correlated with CRP levels in patients with systemic vasculitis." (PMID 34625602, 2021).
T-cell prolymphocytic leukemia (3 papers, 2013 to 2024). A slow-growing type of leukemia (blood cancer) in which too many lymphocytes are found in the bone marrow and/or blood. "T-cell prolymphocytic leukemia (T-PLL) is a rare and extremely aggressive disease characterized by the clonal expansion of mature CD4+ T-cells, leaving patients with limited therapeutic options and poor clinical outcomes." (PMID 39769335, 2024). "Likewise, double CD4+ CD8+ is very rare, and should prompt a consideration of T-cell prolymphocytic leukemia." (PMID 29262669, 2017).
temporal lobe epilepsy (3 papers, 2019 to 2025). A localization-related (focal) form of epilepsy characterized by recurrent seizures that arise from foci within the temporal lobe, most commonly from its mesial aspect. "Among worldwide research, higher expression of TNF-α in CD4+ lymphocytes is reported in patients with temporal lobe epilepsy than controls." (PMID 32403392, 2020). "Previous reports also suggest decreased levels of CD4+ T cells in patients with temporal lobe epilepsy and altered levels of CD8 have been observed in experimental models of SE." (PMID 31333561, 2019).
tenosynovitis (3 papers, 2022 to 2025). Inflammation of the synovial lining of a tendon sheath. "Therefore, we next examined whether the CD4+ or CD8+ T lymphocytes infiltrate the tendon tissues following ARV-induced tenosynovitis by using flow cytometry." (PMID 35369435, 2022).
testicular germ cell tumor (3 papers, 2022 to 2024). A germ cell tumor arising from the testis. "The expression level of CD24 was negatively correlated with the activation of CD4+ and CD8+ T cells in testicular germ cell tumors (TGCT), THCA, CESC, and KIRP." (PMID 39791710, 2024). "In testicular germ cell tumors (TGCT), METTL3 expression was significantly downregulated in TGCT tissues, and its level correlated positively with patient survival rates and levels of tumor-infiltrating CD8+ T cells, CD4+ T cells, and NK cells." (PMID 35296338, 2022).
Trichomonas infection (3 papers, 2014 to 2017). "Furthermore, previous studies have reported that trichomoniasis is associated with a 1.5- to 3-fold increased risk of HIV infection T. vaginalis infection causes an inflammatory response by recruiting CD4+ T cells and macrophages to the vaginal and cervical mucosa." (PMID 28346531, 2017).
unstable angina pectoris (3 papers, 2013 to 2022). "This study aimed to assess the effects of trimetazidine on periprocedural microRNA-21 expression by CD4+ T lymphocytes in patients with unstable angina pectoris." (PMID 29285227, 2017). "Moreover, CD4/CD8 ratio may be related to coronary plaque instability in unstable angina pectoris patients." (PMID 35681174, 2022).
urolithiasis (3 papers, 2013 to 2025). Stone(s) within the urinary tract. "For the Treg cell panel, two traits were linked with increased urolithiasis risk: CD4 Treg %T cell (IVW: OR = 1.060; 95% CI: 1.015, 1.108; p = 0.009) and activated and resting Treg AC (IVW: OR = 1.058; 95% CI: 1.018, 1.100; p = 0.004)." (PMID 40612664, 2025). "First, we found 4-OH-CHT partly negatively mediated the associations between CD4 Treg %T cells and urolithiasis, and the proportions were −11.1%." (PMID 40612664, 2025). "In the maturation stages of the T cell panel, CD3 on TD CD4+ was linked with decreased urolithiasis risk (IVW: OR = 0.963; 95% CI: 0.939, 0.986; p = 0.002)." (PMID 40612664, 2025). "Our finding that B cell traits, Tregs panel, and one trait of CDC panel were linked with increased urolithiasis risk, including IgD-CD24-%lymphocyte, CD24 on transitional B cells, CD25 on IgD+ CD38-naïve, CD4 Treg% T cell, activated and resting Treg AC, and CD11c on myeloid DC." (PMID 40612664, 2025).
urticaria (3 papers, 2021 to 2025). A vascular reaction of the skin characterized by erythema and wheal formation due to localized increase of vascular permeability. "We identified that HLA DR+ CD4+AC, CD45 on CD8br, and HLA DR on plasmacytoid DCs were associated with an increased risk of urticaria, while CD8dim NKT %lymphocyte served as a protective factor against urticaria." (PMID 39606225, 2024). "Specifically, we identified that HLA DR+ CD4+AC, CD45 on CD8br, and HLA DR on plasmacytoid DCs were associated with an increased risk of urticaria." (PMID 39606225, 2024). "In conclusion, our MR analysis results indicated that HLA DR+ CD4+AC, CD45 on CD8br, and HLA DR on plasmacytoid DC increased the risk of urticaria, but CD8dim NKT %lymphocyte may lead to decreased risk of urticaria." (PMID 39606225, 2024).
viral warts (3 papers, 2015 to 2025). "A 50-year-old man with a background of idiopathic CD4+ lymphocytopenia (ICL) was successfully treated with acitretin monotherapy for recalcitrant viral warts on the hands and right cheek." (PMID 40584954, 2025). "CD4+ lymphocytes play an important role in enabling host responses to human papillomavirus (HPV) and, consequently, lower CD4 counts correspond to a higher risk of chronic HPV infection, including viral warts." (PMID 40584954, 2025). "Recent studies have shown that inborn errors of immunity conferring a predisposition to common warts and anogenital HPV lesions largely overlap, and that they impair host cellular immunity, including that mediated by CD4+ T cells, in particular." (PMID 35562936, 2022). "In general, the average CD4+ cell count in HIV-positive patients with viral warts (101 cells/μL) is less than those without viral warts (mean = 294 cells/μL)." (PMID 26239127, 2015).
vitritis (3 papers, 2011 to 2022). "At the peak of vitritis (day 7 post-infection), there was a marked difference in the number of antigen-specific CD4+ T cells infiltrating the retinas of sTg-IRBP:HELlo and sTg-IRBP:HELhi mice, where the latter contained ~50-fold more HEL-specific CD4+ T cells (p < 0.0001)." (PMID 29079770, 2017).
vulvar cancer (3 papers, 2021 to 2024). "Terminally Differentiated CD4+ T cell Absolute Count (OR=3.135, 95%CI:1.247-7.883, P=0.015) and HLA DR on B cell (OR=1.391, 95%CI:1.115-1.736, P=0.003) were correlated with increased vulvar cancer risk." (PMID 38746677, 2024). "At CD4 counts of ≥ 200 cells/mm3, 61.7% of women had early-stage cancer, while 38.3% had late-stage vulvar cancer." (PMID 34691768, 2021). "Of those with CD4 counts of > 200 cells/mm3, 61.7% had early-stage vulvar cancer, while 38.3% had late-stage disease (P = 0.048)." (PMID 34691768, 2021). "Women with higher CD4 counts (≥ 200 cells/mm3) generally presented with early-stage vulvar cancer." (PMID 34691768, 2021).
Acanthamoeba infection (2 papers, 2018 to 2022). "Also, CD4+ T lymphocytes and CD3+/CD4+ and CD3+/CD8+ lymphocyte counts during each stage of acanthamoebiasis were shown to be upregulated." (PMID 30236160, 2018).
acid reflux (2 papers, 2014 to 2024). "Also, the CD4+CD103+ percentage in ex vivo cultures of biopsies obtained from Reflux Esophagitis (RE) (45±19%) was not statistically different from ex vivo cultures of normal looking distal esophagus (C SQ 2 cm) (61±7%)." (PMID 25170842, 2014).
Addison’s disease (2 papers, 2021 to 2025). "Addison’s disease patients often exhibit an altered distribution of CD4+ T cell subtypes, with an increased percentage of late-activated T cells expressing HLA-DR (a Class II major histocompatibility complex [MHC] isotype), which is required for exogenous antigen presentation." (PMID 34239993, 2021).
adrenal tumor (2 papers, 2021 to 2022). "Our results indicated the heterogeneity of the immune system between different samples, and CD4+ T cells with the high expression level of IL-7R might be related to adrenal tumor progression, apoptosis, or factors influencing progression such as immune activation." (PMID 34905486, 2021). "We decided to study the relationship between the CD4 count and the T11 tumor instead of the adrenal tumor because we did not arrange abdominal CT after 2016 and adrenal tumor size could not be evaluated very well in the spinal MRI." (PMID 35141174, 2022).
age-related macular degeneration (2 papers, 2021 to 2023). Age-related loss of vision in the central portion of the retina (macula), secondary to retinal degeneration. "The IFN-γ and IL-17 expression of CD4+ T cells was significantly increased in patients with age-related macular degeneration." (PMID 36658547, 2023). "Furthermore, immunochemical examination of human eye samples of age-related macular degeneration showed the presence of the leukocyte antigens CD45, CD4, CD8, CD14, and CD83 in the choroid." (PMID 34963463, 2021).
agranulocytosis (2 papers, 2014 to 2015). "CD4+/CD8+ ratio in infiltrated organs in patients with agranulocytosis and PRCA-associated CD8+ T-cell expansion." (PMID 24618699, 2014).
Alagille syndrome (2 papers, 2012 to 2018). "Thus, JAG1 mutations, like those seen in Alagille syndrome, are likely to alter T cell development within the thymus and modify effector CD4 T cell differentiation in the peripheral lymphoid organs." (PMID 22937766, 2012).
alcoholic liver diseases (2 papers, 2017 to 2023). A disorder caused by damage to the liver parenchyma due to alcohol consumption. "Patients with alcoholic liver disease also show increased populations of CD4+CD57+ and CD8+CD57+ T cells in the peripheral blood." (PMID 28852648, 2017). "Previous studies have revealed increased numbers of both CD4+ and CD8+ T cells in the portal and sinusoidal regions of the liver in patients with alcoholic liver disease, such as alcoholic hepatitis and cirrhosis." (PMID 28852648, 2017). "In CD4+ and CD8+ T cells, a subset of CD57+ T cells showed higher expression levels of IFN-γ and tumor necrosis factor- (TNF-) α than those in CD57− T cells, in both healthy controls and patients with alcoholic liver disease." (PMID 28852648, 2017). "The non-functional anti-CD4 IgGs in untreated patients likely are induced by a viremia-mediated cytokine storm, because inflammation can induce non-functional autoantibodies non-specifically, as shown in alcoholic liver disease." (PMID 37027536, 2023).
anaplastic thyroid cancers (2 papers, 2020 to 2025). "We find that mouse BrafV600E-driven anaplastic thyroid cancers (ATC) respond markedly to the RAF + MEK inhibitors dabrafenib and trametinib (dab/tram) and that this is associated with upregulation of MhcII in cancer cells and increased CD4+ T-cell infiltration." (PMID 40828595, 2025).
aneurysmal disease (2 papers, 2020 to 2022). "They found that HIV-associated vasculopathy primarily occurred in PLWH with low CD4 counts and was almost equally likely to present as an occlusive disease (51%) versus aneurysmal disease (49%)." (PMID 36264482, 2022). "In one study, serial echocardiography showed an increased left ventricular dilation in the CD4 knockout mice compared with the wild type control for up to 56 days after MI 7, suggesting a protective role of CD4+ T-cells in facilitating cardiac repair." (PMID 32724455, 2020).
angiosarcoma (2 papers, 2011 to 2024). A malignant tumor arising from the endothelial cells of the blood vessels. "Furthermore, a recent case report suggests that an immune response contributes to tumour eradication also in humans: CD4+ and CD8+ T-cell infiltrates have been observed in lesions after Fotolon-mediated PDT of recurrent angiosarcoma, which underwent remission after therapy." (PMID 21863026, 2011).
ankylosis (2 papers, 2021 to 2023). Fixation and immobility of a joint. "It was observed that CD4-CKO mice spontaneously developed bone disease 6 months after birth, which originated with an enlarged pelvic incidence angle and knee stiffness, and progressed to hip and knee kyphosis and ankylosis, respectively." (PMID 37048045, 2023). "The CD4-CKO mice developed bone disease spontaneously, which started with enlarged pelvic incidence angle and knee stiffness at 7 months, followed by kyphosis and ankylosis of hip and knee joint." (PMID 34764263, 2021).
anorexia nervosa (2 papers, 2019 to 2022). A disorder most often seen in adolescent females characterized by a refusal to maintain a minimally normal body weight, an intense fear of gaining weight, a disturbance in body image, and, in postmenarcheal females, the development of amenorrhea. "When comparing the immune system changes in protein malnutrition and anorexia nervosa, it is suggested that anorexia nervosa is associated with increased pro-inflammatory cytokines, an elevated CD4/CD8 ratio, and increased T cell proliferation." (PMID 31717370, 2019). "The CD4/CD8 ratio in anorexia nervosa is seemingly increased, and this appears due to a greater reduction in CD8 counts compared to CD4 counts." (PMID 31717370, 2019).
aortic atherosclerosis (2 papers, 2022). A atherosclerosis that involves the aorta. "In ApoE–/– mice, immunization with P210-PAMs dampened P210-specific CD4+ T cell proliferative response and CD8+ T cell cytolytic response, modulated macrophage phenotype, and significantly reduced aortic atherosclerosis." (PMID 35536648, 2022).
aortic valve calcification (2 papers, 2019 to 2024). "Moreover, macrophages, CD4‐ and CD8‐positve T cells, B cells and NK cells are positively associated with pressure gradients and aortic valve calcification." (PMID 38566328, 2024). "Meanwhile, positive correlations of CD4+CD8dim and CD8+CD4dim with Agatston calcium score for MAS patients demonstrated their potential interconnection with aortic valve calcification process." (PMID 31402927, 2019).
arteriosclerosis obliterans (2 papers, 2014 to 2022). Common occlusive arterial disease which is caused by atherosclerosis. "RAC1 promotes CD4+ T cell migration in arteriosclerosis obliterans." (PMID 36211372, 2022). "The migration of CD4+ T cells plays an important role in arteriosclerosis obliterans (ASO)." (PMID 24743945, 2014).